SCN9A (sodium voltage-gated channel alpha subunit 9)
Diseases named in the same sentence as SCN9A in open-access papers (continued):
Sharing a sentence is not in itself a finding about the gene and the disease.
neurodevelopmental disorder (2 papers, 2021 to 2024). A behavioral and cognitive disorder with onset during the developmental period that involves impaired or aberrant development of intellectual, motor, or social functions. "Together, these studies suggest that mutations of SCN9A might have pleiotropic clinical effects and play a role in neurodevelopmental disorders in addition to pain-related disorders." (PMID 34947986, 2021). "An indirect interaction between SCN9A and CACNA2D1 may exist through LAT1 (SLC7A5) as a common regulator of both; indeed, CIP can be present in patients with CACNA2D1 variants as a part of a more syndromic and severe neurodevelopmental disorder." (PMID 39156962, 2024).
SCN9A also shares sentences with these, for which no sentence is quoted: Pain (15 papers); neuropathic pain (13); neuroma (7); non-small cell lung carcinoma (6); pulpitis (6); trigeminal neuralgia (6); cervical cancer (5); migraine (5); febrile seizures (4); Obesity (4); burning mouth syndrome (3); congenital insensitivity to pain (3); familial hemiplegic migraine (3); inflammation (3); atrial fibrillation (2); autonomic neuropathies (2); bone cancer (2); cardiac arrhythmia (2); Chronic pain (2); colon cancer (2); endometrial cancer (2); familial episodic pain syndrome (2); Headache (2); heart failure (2); Myotonia (2); schizophrenia (2); tuberculosis (2); viral infection (2); acne (1); Angelman syndrome (1).
A further 92 diseases each share a sentence with SCN9A in 1 paper.